RBM20 (RNA binding motif protein 20)
Diseases named in the same sentence as RBM20 in open-access papers (continued):
Sharing a sentence is not in itself a finding about the gene and the disease.
autosomal dominant dilated cardiomyopathy (1 paper, 2022). Dilated cardiomyopathy, characterized by dilation and contractile dysfunction of the left and right ventricles, with an autosomal dominant pattern of inheritance. "Pathogenic variants in PDZD7 and RBM20 are associated with autosomal recessive non-syndromic hearing loss and autosomal dominant dilated cardiomyopathy, respectively, suggesting that these variants are unlikely likely to contribute to the clinical presentation." (PMID 35911904, 2022).
developmental delay (1 paper, 2026). "A homozygous Ser529Arg substitution in the RNA recognition domain of RBM20 was recently identified in two brothers of consanguineous families affected by epilepsy and developmental delay." (PMID 41524378, 2026).
dilation (1 paper, 2021). "Left ventricular dilation and electrical abnormalities were present in these RBM20-deficient rats, showing comparatively similar pathologies as RBM20-deficient humans." (PMID 34575212, 2021).
Hypertension (1 paper, 2025). The presence of chronic increased pressure in the systemic arterial system. "Furthermore, our data provide proof‐of‐concept evidence that targeting RBM20 to reduce arterial stiffness through titin isoform switching may benefit aging‐ or hypertension‐associated arterial stiffness and vascular diseases." (PMID 40119572, 2025). "Next, we evaluated whether increased arterial compliance in Ang II‐treated Rbm20 KO animals benefits hypertension‐induced cardiac remodeling." (PMID 40119572, 2025). "Our findings suggest that a similar strategy targeting the RBM20‐titin axis to fine‐tune VSMC stiffness could alleviate hemodynamic stress on the heart and lower the risk of end‐organ damage in the context of hypertension." (PMID 40119572, 2025).
hypopharyngeal cancer (1 paper, 2023). Carcinoma, predominantly squamous cell, arising from the epithelial cells of the hypopharynx. "In our samples, KMT2C, which participates in protein binding, has pathogenic mutations in all samples, and the expression of RBM20 is related to the survival of patients with hypopharyngeal cancer, indicating that they are likely to be related to the pathogenesis of hypopharyngeal cancer." (PMID 36596842, 2023). "In conclusion, we found possible therapeutic targets for hypopharyngeal cancer, especially RBM20 and KMT2C." (PMID 36596842, 2023). "RBM20 has the most significant correlation with hypopharyngeal cancer, and it is likely to be the driver gene of hypopharyngeal cancer." (PMID 36596842, 2023). "After verifying the selected 53 driver genes using the UALCAN database, we found that RBM20 was highly expressed in the hypopharyngeal cancer tissue." (PMID 36596842, 2023). "The high expression of RBM20 predicts a worse OS in patients with hypopharyngeal cancer, indicating that RBM20 is likely to be related to the pathogenesis or disease progression of hypopharyngeal cancer." (PMID 36596842, 2023). "However, more adequate descriptive and functional studies are required to fully reveal the pathogenic roles of RBM20 and KMT2C in the pathophysiology of hypopharyngeal cancer." (PMID 36596842, 2023). "We performed whole-exome sequencing on 10 patients with hypopharyngeal cancer and screened out some genes that may be related to the pathogenesis of hypopharyngeal cancer, including a great number of novel mutations that have not been reported, especially mutations in RBM20 and KMT2C." (PMID 36596842, 2023).
hypothyroidism (1 paper, 2020). Abnormally low levels of thyroid hormone. "In that regard, hypothyroidism could contribute to disease severity by regulating RBM20 expression and missplicing of downstream splicing targets, as it is known that RBM20 levels correlate with the amount of missplicing of its targets." (PMID 32789749, 2020).
idiopathic dilated cardiomyopathy (1 paper, 2025). Decreased function of the heart associated with cardiac enlargement and congestive heart failure, of unknown cause. "Furthermore, loss-of-function mutations in this splicing factor led to increased expression of the N2BA isoform, and mice carrying RBM20 mutations developed idiopathic dilated cardiomyopathy." (PMID 40650017, 2025).
metabolic syndrome (1 paper, 2025). A cluster of metabolic risk factors for CARDIOVASCULAR DISEASES and TYPE 2 DIABETES MELLITUS. "Here, we optimized RBM20-ASO dosing in a HFpEF mouse model that closely mimics human disease, characterized by metabolic syndrome and comorbidities, but without primary defects in titin or RBM20." (PMID 41104480, 2025).
myofibrillar myopathy (1 paper, 2025). "Truncating variants in TTN are strongly associated with DCM, while mutations in DSP, LMNA, MYH7, RBM20, TNNT2, BAG3, and FLNC (the latter being linked to myofibrillar myopathy) are also commonly implicated." (PMID 39857686, 2025).
myotonic dystrophy (1 paper, 2022). An inherited progressive disorder affecting the muscles. "The present experiment explained that this abnormal exon 11 splicing was not caused by the RBM20 variant but was possibly caused by myotonic dystrophy." (PMID 36198914, 2022).
neuroblastoma (1 paper, 2020). Neuroblastoma (NB) is the most common solid, extracranial childhood tumor. "For example, in the large SEQC cohort, RBM11, RBM20, RBMX2 were all upregulated in stage 4 neuroblastoma, compared to 4S with RBM47 being downregulated." (PMID 32707690, 2020).
papillary thyroid cancer (1 paper, 2018). "Identification of two of these actionable variants (RBM20 and SDHB) led to screening that identified associated findings (evidence of DCM and papillary thyroid cancer, respectively) and may have a significant impact on these participants’ long-term health." (PMID 30487145, 2018).
schizophrenia (1 paper, 2015). A major psychotic disorder characterized by abnormalities in the perception or expression of reality. "As outlined in S11 Table, seven of these genes have, to varying degrees, plausible links to cognition (i.e. DGKB, NPS, VPS13B, RBM20, ABHD4, ESRRB, and DOPEY2), with some active in systems implicated in schizophrenia pathology (NPS, DGKB, ABHD4, ESRRB)." (PMID 25860228, 2015).
Sciatica (1 paper, 2021). Pain in the lower back and hip radiating in the distribution of the sciatic nerve. "The roles of SLC8A1, RBM20, GPER1, IL27, SOCS1, and GRTP1-AS1 in sciatica or in relieving sciatica are currently unknown." (PMID 33573686, 2021).
ventricular dilatation (1 paper, 2018). "RBM20 mutations identified in DCM patients and their symptoms other than ventricular dilatation." (PMID 30547036, 2018).
heart diseases (18 papers, 2018 to 2026). "This work highlights a common requirement for RBM20-dependent transcriptome regulation in cardiomyocytes and neurons and demonstrates that a major genetic risk factor of heart disease impacts neuronal gene expression." (PMID 41524378, 2026). "In the following section, we will highlight several AS factors with cardiac disease-associated genetic variants, beginning with RBM20, and their emerging functions beyond splicing." (PMID 39773891, 2025). "The discovery that certain genetic variants in RBM20 also promote the formation of pathogenic granules in the cytoplasm establishes a new paradigm for cardiac disease." (PMID 39773891, 2025). "Among the mRBP-coding genes with a high HSS, we found genes coding for well-known heart-disease causing splicing factors, such as RBM20 (HSS = 10.2) and RBFOX1 (HSS = 11.4)." (PMID 34273561, 2022). "RBM20 alterations have been observed in 2–3% of FDCM cases, and the altered expression of RBM20 can shift the expression pattern of titin transcript variants, leading to cardiac diseases, such as FDCM." (PMID 33671899, 2021). "TTN is the most relevant gene regulated by RBM20 and truncating variants in titin are major determinants of heart disease, accounting for ~30% of DCM." (PMID 32276354, 2020). "The iPSCs harboring RBM20 human mutations offer a great opportunity for modeling heart disease in vitro." (PMID 32276354, 2020). "Mutations or altered expression of RBM20 can lead to the shift in the expression pattern of titin transcript variants, which are associated with cardiac diseases, including DCM." (PMID 32276354, 2020). "RNA binding motif 20 (RBM20) is a key regulator of pre-mRNA splicing of titin and other genes that are associated with cardiac diseases." (PMID 31614708, 2019). "The RBM20 associated heart disease is mainly based on the mis-splicing of pivotal cardiac genes, among which titin is recognized as a major human disease gene." (PMID 29304022, 2018). "An important question is whether this is unique to RBM20 or whether localization-disrupting genetic variants in other RNA-binding proteins, such as AS factors, could also cause cardiac disease through such a mechanism." (PMID 39773891, 2025). "We highlight the identification of pathogenic RBM20 granules as a causative agent in cardiac disease and discuss whether such a mechanism could be shared among localization-disrupting variants in AS factors." (PMID 39773891, 2025). "Until recently, only mutations in RBM20 has been linked to heart disease." (PMID 29304022, 2018). "As effective regulators of cardiac stiffness based on titin, RBM20 provides novel strategies to treat heart diseases with impaired cardiac compliance, especially HFpEF." (PMID 35783855, 2022). "RBM20, as a splicing regulator, also regulates circRNA production from a handful of other genes in hearts, whose involvement in heart disease remains to be tested." (PMID 32429565, 2020). "Our study provides a potential therapeutic target for the treatment of cardiac diseases in RBM20-mediated pre-mRNA splicing." (PMID 31614708, 2019). "In the end, we will discuss the multifunctional role of RBM20 and manipulation of RBM20 as a potential therapeutic target for heart disease." (PMID 29304022, 2018). "In this review, we will focus on the intersection between muscle-specific alternative splicing and heart disease, with a particular emphasis on a muscle-specific splicing factor RBM20 and its regulatory roles in heart disease." (PMID 29304022, 2018). "Since it is known that RBM20 mainly regulates titin alternative splicing, future work can focus on developing therapeutic agents targeting RBM20 to shift titin isoform in heart disease." (PMID 29304022, 2018). "Taken together, future work should be focused on understanding the multi-functional role of RBM20 and developing therapeutic agents targeting RBM20 in heart diseases." (PMID 29304022, 2018).
heart diseases (continued). "Our understanding of the molecular and physiological effects of RBM20 mutations has remained elusive largely due to a lack of appropriate models that are not confounded by heart disease or patient genetics." (PMID 34732726, 2021). "A prominent example is the muscle-specific and cardiac disease-relevant splicing regulator RBM20." (PMID 34879078, 2021). "Direct involvement of RBM20 in heart disease is proved by two orders of evidence." (PMID 32276354, 2020). "In addition, RBM20 expression level varies in patients with heart disease, and its expression correlates with the splicing of RBM20 target genes, which demonstrates RBM20 involvement in disease progression." (PMID 29304022, 2018). "Although it may be advantageous to modulate Rbm20-dependent titin splicing to decrease passive stiffness in certain types of heart disease where passive stiffness is increased, the effect on other Rbm20 targets such as calcium handling genes must be carefully evaluated." (PMID 30051286, 2018). "In this review, we summarize the functional evidences of the role of RBM20 in the regulation of TTN and additional genes involved in heart function and cardiac diseases development." (PMID 32276354, 2020). "Even though the precise role of RBM20 in the hormone-induced change in titin splicing is still not clear, these findings provide novel insights into developing therapeutic agents targeting RBM20 to induce titin isoform switching for treatment of heart disease." (PMID 29304022, 2018).
cardiovascular diseases (7 papers, 2019 to 2025). "Moreover, our data provide proof‐of‐concept evidence that targeting titin‐based VSMC tone through the RBM20‐titin axis may be beneficial for the treatment of cardiovascular diseases caused by or involving increased peripheral vascular resistance." (PMID 40119572, 2025). "Furthermore, we review the current knowledge about the contribution of RBM20 and PTBP1 in heart alternative splicing events, their combinatory role in selecting specific exons and RBM20’s role in cardiovascular diseases." (PMID 32276354, 2020).
tumor (2 papers, 2022 to 2023). "The genes with low expression in the tumor group were CRISP3, FAM3D, SCNN1B, CRISP2, RBM20, PHYHIP, C2orf54, SLC5A1, PTCRA, C15orf59, and ANO10." (PMID 35389773, 2022).
myopathies (1 paper, 2021). "Therefore, whether loss-of-function of RBM20 in skeletal muscle leads to myopathies needs be investigated in future studies." (PMID 33805770, 2021).
neurological diseases (1 paper, 2021). "Hence, these data strongly support a model by which mutant RBM20 impacts alternative splicing through broad non-nuclear 3′ UTR binding and association with P-bodies, a mechanism that is reminiscent of neurological diseases associated with RNA-binding protein cytoplasmic aggregation." (PMID 34732726, 2021).
RBM20 also shares sentences with these, for which no sentence is quoted: catecholaminergic polymorphic ventricular tachycardia (2 papers); Alzheimer disease (1); Behçet’s disease (1); Brugada syndrome (1); cancer (1); COVID-19 (1); craniosynostosis (1); Dravet syndrome (1); Duchenne muscular dystrophy (1); epilepsy (1); familial hypercholesterolemia (1); Fuchs endothelial corneal dystrophy (1); genetic disorders (1); Huntington disease (1); hypoplastic left heart syndrome (1); infection (1); ischemic cardiomyopathy (1); Left ventricular noncompaction cardiomyopathy (1); long QT syndrome 3 (1); muscular dystrophy (1); Myocardial fibrosis (1); myocarditis (1); neurodegenerative disease (1); Obesity (1); polyarteritis nodosa (1); respiratory diseases (1); Skeletal myopathy (1); thyroid (1); type 2 diabetes (1); Vascular Ehlers-Danlos Syndrome (1).
A further 1 disease shares a sentence with RBM20 in 1 paper.